HPGD (15-hydroxyprostaglandin dehydrogenase)
Diseases named in the same sentence as HPGD in open-access papers (continued):
Sharing a sentence is not in itself a finding about the gene and the disease.
Pachydermoperiostosis (6 papers, 2011 to 2023). with prominent pachydermia and minimal-to-absent skeletal changes. "Mutations in HPGD gene are responsible for autosomal recessive primary hypertrophic osteoarthropathy 1 (PHOAR1) and mutations in SLCO2A1 gene are responsible for autosomal recessive primary hypertrophic osteoarthropathy 2 (PHOAR2)." (PMID 30352415, 2018).
cervical cancer (4 papers, 2018 to 2023). A primary or metastatic malignant neoplasm involving the cervix. "In conclusion, down-regulation of HPGD is associated with up-regulation of miR-146b-3p in cervical cancer." (PMID 30333561, 2018). "HPGD was significantly down-regulated in cervical cancer tissues, and conversely, overexpression of HPGD associated with dramatically reduced cancer cell proliferation, migration and anchorage-independent growth." (PMID 30333561, 2018). "While HPGD is clearly implicated in several malignancies, its potential association with cervical cancer development is unknown at present." (PMID 30333561, 2018). "In our investigation, frequent up-regulation of miR-146b-3p was evident in cervical cancer tissues and HPGD identified as its direct target." (PMID 30333561, 2018). "Similar to the effects of HPGD overexpression, down-regulation of miR-146b-3p strongly suppressed proliferation, migration and anchorage-independent growth of cervical cancer cells." (PMID 30333561, 2018). "Here, we detected significant down-regulation of 15-hydroxyprostaglandin dehydrogenase (HPGD) in cervical cancer tissues." (PMID 30333561, 2018). "In view of the decreased expression of HPGD in cervical cancer tissues, the cervical cancer cell lines, HeLa and SiHa, were transduced with lentivirus-HPGD, and the cell colony formation assay conducted." (PMID 30333561, 2018). "miR-146b-3p, which directly targets HPGD, was up-regulated in cervical cancer tissues, contributing to enhanced cell proliferation, migration and anchorage-independent growth." (PMID 30333561, 2018). "HPGD was identified as a direct target of miR-146b-3p displaying up-regulation in cervical cancer tissues." (PMID 30333561, 2018). "Data from the current study disclosed that HPGD expression is remarkably down-regulated in cervical cancer tissues and its overexpression suppresses cell proliferation, migration and anchorage-independent growth." (PMID 30333561, 2018). "In the majority of cervical cancer tissue specimens (60/67), HPGD expression was significantly lower relative to paracancerous tissues." (PMID 30333561, 2018). "Immunohistochemical staining consistently revealed lower numbers of HPGD-positive cells in cervical cancer than normal tissues." (PMID 30333561, 2018). "Our results clearly suggest that the miR-146b-3p/HPGD axis could serve as a promising prognostic and therapeutic target for cervical cancer management." (PMID 30333561, 2018). "Our results collectively suggest that the HPGD/miR-146b-3p axis plays a significant role in cervical cancer and may serve as a potentially effective therapeutic target." (PMID 30333561, 2018). "Hpgd (15-hydroxyprostaglandin dehydrogenase) encodes a member of the short chain nonmetallic enzyme alcohol dehydrogenase protein family, and can activate STAT3 and AKT pathways to promote proliferation, migration and anchorage-independent growth of cervical cancer cells." (PMID 37055764, 2023).
cholangiocarcinoma (4 papers, 2014 to 2021). A carcinoma that arises from the intrahepatic biliary tree (intrahepatic cholangiocarcinoma) or from the junction, or adjacent to the junction, of the right and left hepatic ducts (hilar cholangiocarcinoma). "Moreover, omega-3 polyunsaturated fatty acids (ω-3 PUFA) induce HPGD expression through inhibition of miR-26a and miR-26b, leading to suppression of human cholangiocarcinoma cell growth." (PMID 30333561, 2018). "It plays important roles in the progress of cholangiocarcinoma through targeting PTEN/AKT pathway, TIMP3 (tissue inhibitor of metalloproteinases 3), 15-PGDH (15-hydroxyprostaglandin dehydrogenase), or EMT (epithelial–mesenchymal transition)." (PMID 33805513, 2021). "Interestingly, it has just been reported that the 15-hydroxyprostaglandin dehydrogenase (15-PGDH) mRNA which codes for a key enzyme required for PGE2 degradation, is a direct target of miR-21 in cholangiocarcinoma cells." (PMID 25310697, 2014).
endometriosis (4 papers, 2019 to 2025). The growth of functional endometrial tissue in anatomic sites outside the uterine body. "Decreased expression of HPGD is associated with abnormal prostaglandin metabolism in endometriosis." (PMID 37033258, 2023). "Decreased HPGD expression is associated with abnormal prostaglandin metabolism in endometriosis." (PMID 31692912, 2019). "Consequently, celecoxib has been associated with increased HPGD expression, suggesting it may serve as a biomarker or therapeutic target for reducing the risk of malignancies and the severity of endometriosis." (PMID 40722854, 2025). "HPGD was reported to be involved in the pathophysiology of endometriosis." (PMID 37033258, 2023). "However, the increased HPGD expression in normal peritoneal tissues may be lower than that observed in malignant or inflammatory tissues, as this study did not demonstrate HPGD protein expression by IHC, unlike previous findings in cancer or endometriosis." (PMID 40722854, 2025).
pachydermia (4 papers, 2019 to 2023). "However, phenotypes such as arthritis, joint involvement, and pachydermia are more prominent in patients homozygous for SLCO2A1 mutations than HPGD homozygous or compound heterozygous-affected individuals." (PMID 36833358, 2023). "However, in humans, reports of HPGD and SLCO2A1 mutation cases have only been focused on the typical features such as digital clubbing, periostosis and pachydermia." (PMID 31063976, 2019). "In addition to typical clinical features (digital clubbing, periostosis and pachydermia), the patient demonstrated a new clinical manifestation, a giant soft tissue tumor on the left lower leg which has not been reported in HPGD-mutated PHO patient before." (PMID 31063976, 2019). "In addition to typical clinical features including digital clubbing, periostosis, pachydermia and acro-osteolysis, the patient presented an atypical manifestation, giant soft tissue tumors at both lower legs which have not been reported in HPGD-mutated PHO patient before." (PMID 31063976, 2019).
pulmonary fibrosis (4 papers, 2020 to 2023). Chronic progressive interstitial lung disorder characterized by the replacement of the lung tissue by connective tissue, leading to progressive dyspnea, respiratory failure, or right heart failure. "Thus, we hypothesized that increasing endogenous PGE2 by systemic administration of well-tolerated small molecules that inhibit the PGE2-degrading enzyme 15-hydroxyprostaglandin dehydrogenase (15-PGDH) would prevent pulmonary fibrosis in bleomycin-treated mice." (PMID 32669620, 2020). "This study lays the foundation for the development of a sustained release platform for the delivery of (+)SW033291, a potent, small-molecule inhibitor of the 15-hydroxyprostaglandin dehydrogenase (15-PGDH) enzyme, which has previously demonstrated efficacy in a murine model of pulmonary fibrosis." (PMID 35056981, 2021).
Sepsis (4 papers, 2023 to 2025). Sepsis is defined as life-threatening organ dysfunction caused by a dysregulated host response to infection. "Inhibition of HPGD in sepsis reduced lipid peroxidation and alleviated LPS-induced kidney injury." (PMID 39628572, 2024). "Furthermore, the downregulation of HPGD may result in prolonged inflammation due to the decreased inactivation of pro-inflammatory prostaglandins, exacerbating the systemic inflammation characteristic of sepsis." (PMID 40520167, 2025). "The results showed significantly higher levels of OLAH, HPGD, and LY96 in sepsis patients compared to those with preoperative conditions or pneumonia, increased by 95.16-, 6.58-, and 2.89-fold, respectively, while ABLIM1 was downregulated by 7.33-fold." (PMID 39628572, 2024). "The refined model, comprising genes OLAH, LY96, HPGD, and ABLIM1, demonstrated high predictive accuracy for 28-day mortality and excelled in early sepsis detection." (PMID 39628572, 2024).
type 2 diabetes mellitus (4 papers, 2014 to 2024). A type of diabetes mellitus that is characterized by insulin resistance or desensitization and increased blood glucose levels. "This study focused on exploring the effects of SW033291, an inhibitor of 15-hydroxyprostaglandin dehydrogenase, on type 2 diabetes mellitus (T2DM) mice from a comprehensive perspective." (PMID 39330516, 2024). "By Western-blotting and quantitative qRT-PCR, mPGES-1, mPGES-2, cPGES and 15-hydroxyprostaglandin dehydrogenase (15-PGDH) remain unaltered following six weeks of diabetes." (PMID 24984018, 2014). "Patients with type 2 diabetes exhibit reduced HPGD expression in Treg cells." (PMID 35983515, 2022).
Obesity (3 papers, 2021 to 2022). Accumulation of substantial excess body fat. "Treg cells in adipose tissue express the enzyme hydroxyprostaglandin dehydrogenase (HPGD), which converts prostaglandin E2 (PGE2) into 15-keto PGE2, and Treg cell-specific loss of HPGD exacerbates adipose inflammation and insulin resistance in response to diet-induced obesity." (PMID 34837070, 2022).
pancreatic ductal adenocarcinoma (3 papers, 2019 to 2021). An infiltrating adenocarcinoma that arises from the epithelial cells of the pancreas. "In pancreatic ductal adenocarcinoma, TAMs prevent 15-hydroxyprostaglandin dehydrogenase (15-PGDH) expression by secreting IL-1β and are associated with poor prognosis of patients." (PMID 31629410, 2019). "The accumulation of prostaglandin E2 (PGE2) by inhibition of the degradation enzyme 15-hydroxyprostaglandin dehydrogenase (15-PGDH) induces progression of pancreatic ductal adenocarcinoma (PDAC)." (PMID 31590252, 2019). "In pancreatic ductal adenocarcinoma, TAM-derived IL-1β prevents expression of 15-hydroxyprostaglandin dehydrogenase (15-PGDH) and low 15-PGDH is correlated with more advanced tumor stage and lymph node metastasis." (PMID 34771482, 2021).
colorectal tumors (2 papers, 2023 to 2025). "were associated with prevention/protection against large intestine neoplasms, including GUCA2A, CDX2, VDR, VEFGA, GSTM1, HPGD, and PPARG." (PMID 37296943, 2023). "Furthermore, TTI-101 treatment also led to the upregulation of important genes such as GUCA2A, CDX2, VDR, GSTM1, HPGD, and PPARG that have been shown by others to be associated with the prevention of large intestine neoplasms." (PMID 37296943, 2023).
endometrial adenocarcinoma (2 papers, 2019 to 2023). "In line with the previous studies, we found decreased HPGD expression in endometrial adenocarcinoma tissue, which might be suppressed by upregulated miR-218-5p." (PMID 31692912, 2019). "Besides, the decreased expression of HPGD might be regulated by the miR-218-5p in endometrial adenocarcinoma tissue." (PMID 37033258, 2023).
endometrial cancer (2 papers, 2019 to 2020). Primary or metastatic malignant neoplasm involving the endometrium (mucous membrane that lines the endometrial cavity). "In addition, it has been shown that increased levels of ALOX5 and decreased levels of 15-hydroxyprostaglandin dehydrogenase (HPGD) are associated with adverse prognosis in endometrial cancer." (PMID 33348841, 2020).
glioma (2 papers, 2014 to 2023). A benign or malignant brain and spinal cord tumor that arises from glial cells (astrocytes, oligodendrocytes, ependymal cells). "At the same time, in gliomas (GBM and lower grade glioma), there were no changes in 15-PGDH/HPGD expression relative to healthy brain tissue." (PMID 36765904, 2023).
lymph node metastasis (2 papers, 2021 to 2025). "In PDAC, IL-1β released by TAMs suppressed the expression of 15-hydroxyprostaglandin dehydrogenase (15-PGDH), an enzyme inversely associated with tumor advancement, presence of lymph node metastasis and nerve invasion, and poor prognosis of patients." (PMID 40083710, 2025).
nail disorder (2 papers, 2019 to 2022). A disease involving the nail. "The genes associated with human hereditary nail disorders are listed as HPGD, RSPO4, PLCD1, COL7A1 and FZD6." (PMID 30642273, 2019). "Pathogenic variants of five genes (RSPO4, FZD6, HPGD, PLCD1, and COL7A1) have been reported to cause congenital pure nail disorders, among which FZD6 (frizzled class receptor 6) and RSPO4 are responsible for most of the cases." (PMID 36421794, 2022).
pancreatic cancer (2 papers, 2016 to 2022). "The downregulation of HPGD caused by activation of interleukin-1β led to a poor prognosis in pancreatic cancer patients, and reduction of HPGD expression was associated with tumorigenesis." (PMID 35317779, 2022).
pneumonia (2 papers, 2022 to 2024). An acute, acute and chronic, or chronic inflammation focally or diffusely affecting the lung parenchyma, caused by an infection in one or both of the lungs (by bacteria, viruses, fungi, or mycoplasma.). "15-hydroxyprostaglandin dehydrogenase (15-PGDH) is involved in pneumonia, while its relationship with SAP has yet to be determined." (PMID 35720081, 2022).
triple-negative breast carcinoma (2 papers, 2020 to 2025). An invasive breast carcinoma which is negative for expression of estrogen receptor (ER), progesterone receptor (PR), and human epidermal growth factor receptor 2 (HER2). "However, in this study, HPGD expression was significantly decreased in triple negative breast cancer compared to other molecular subtypes." (PMID 33210098, 2020). "One study showed that high, rather than low, HPGD expression was significantly associated with poor outcome in triple negative breast cancer." (PMID 33210098, 2020). "To investigate the role of 15-hydroxyprostaglandin dehydrogenase (HPGD) in regulating cell proliferation and tumor growth, we stably transduced three human triple-negative breast cancer (TNBC) cell lines—MDA-MB231, MDA-MB436, and MDA-MB468—with lentiviral vectors carrying HPGD." (PMID 40076539, 2025).
acute kidney injury (1 paper, 2020). Sudden and sustained deterioration of the kidney function characterized by decreased glomerular filtration rate, increased serum creatinine or oliguria. "The present study aimed to investigate the effect of 15-hydroxyprostaglandin dehydrogenase (15-PGDH), a key enzyme in the degradation of prostaglandins, on lipopolysaccharide (LPS)-induced acute kidney injury (AKI) in mice." (PMID 32231583, 2020).
anaemia (1 paper, 2019). "As to another 2 patients who had HPGD mutations (PHOAR1), the GI disorders only manifested diarrhea without anaemia or hypoalbuminemia." (PMID 31878983, 2019).
cleft palate (1 paper, 2020). Cleft palate is a fissure type embryopathy that affects the soft and hard palate to varying degrees. "In case 30, we could not identify a gene specifically associated with the observed cleft palate; we only identified an autosomal recessive gene, HPGD, associated with a high-arched palate and without dose-sensitive reports." (PMID 32863884, 2020).
colorectal adenoma (1 paper, 2023). An adenoma that arises from the colon or rectum. "The expression of HPGD encoding 15-PGDH, involved in the degradation of PGE2 to a less active metabolite, was not significantly different among colorectal adenomas and the right colon and rectum biopsies." (PMID 37173923, 2023).
colorectal polyp (1 paper, 2023). "None of the PTGS1, PTGS2, or HPGD SNP genotypes, including rs4837960 and rs2745557, reached univariate statistical significance for a difference in total colorectal polyp number or adenomatous polyp number between individuals who received either active EPA or placebo EPA." (PMID 37756582, 2023).
esophageal cancer (1 paper, 2022). A primary or metastatic malignant neoplasm involving the esophagus. "However, a previous studies reported a decrease in HPGD expression in ESCC tissues, and in an isolated human metastasizing esophageal cancer cell line, suggesting that HPGD may contribute to ESCC development." (PMID 35317779, 2022).
GI hemorrhage (1 paper, 2019). "In a study including 43 Chinese patients, watery diarrhea occurred in more than half of the patients with either HPGD or SLCO2A1 gene mutation, but SLCO2A1 mutated patients had a higher frequency of GI hemorrhage." (PMID 31878983, 2019).
hepatocellular carcinoma (1 paper, 2018). A malignant tumor that arises from hepatocytes. "HPGD has been shown to regulate the 15-keto-PGE2/peroxisome proliferator-activated receptor-γ/p21 (WAF1/Cip1) signaling pathway to suppress hepatocellular carcinoma growth." (PMID 30333561, 2018).
Hirsutism (1 paper, 2011). Abnormally increased hair growth referring to a male pattern of body hair (androgenic hair). "The patient also presented with idiopathic hirsutism which can probably be explained by the recently identified mutations in HPGD (4q33-q34) that encodes for 15-hydroxyprostaglandin dehydrogenase which is the main enzyme of prostaglandin degradation." (PMID 21831298, 2011).
intestinal tumors (1 paper, 2025). "The homeostatic accumulation of PGE2 in intestinal tumors arises from enhanced COX-2-driven biosynthesis and reduced degradation due to the pervasive loss of 15-hydroxyprostaglandin dehydrogenase (15-PGDH) in CRC." (PMID 41488637, 2025).
leukemia (1 paper, 2022). A malignant (clonal) hematologic disorder, involving hematopoietic stem cells and characterized by the presence of primitive or atypical myeloid or lymphoid cells in the bone marrow and the blood. "Other miR-139 targets that are described in leukemia and some other types of cancer are BTG3, the RNA-binding protein ELAVL1, Tetraspanin-3 (TSPAN3), MAX Network Transcriptional Repressor (MNT), 15-Hydroxyprostaglandin Dehydrogenase (HPGD) and Protein Tyrosine phosphatase Receptor Type-T (PTPRT)." (PMID 35269391, 2022).
metastatic prostate carcinoma (1 paper, 2017). A carcinoma that arises from the prostate gland and has spread to other anatomic sites. "HPGD was highly expressed in androgen receptor (AR)–overexpressing advanced tumors, as well as in metastatic prostate cancers." (PMID 29299133, 2017).
periodontitis (1 paper, 2023). An acute or chronic inflammatory process that affects the tissues that surround and support the teeth. "The SPAG4, CCDC69, KRT10, CXCL12, HPGD, CLDN20 and CCL187 genes were the most important cross-talk genes between periodontitis and IgAN." (PMID 36793719, 2023). "By taking the intersection of WGCNA important module genes and DEGs, we found that the SPAG4, CCDC69, KRT10, CXCL12, HPGD, CLDN20 and CCL187 genes were the most important cross-talk genes between periodontitis and IgAN." (PMID 36793719, 2023). "By taking the intersection of WGCNA important module genes and DEGs, we found that the SPAG4, CCDC69, KRT10, CXCL12, HPGD, CLDN20 and CCL187 genes were the most important cross-talk genes between periodontitis and IgAN, and these genes may be related to kinase regulator activity." (PMID 36793719, 2023).
renal carcinoma (1 paper, 2018). A carcinoma arising from the epithelium of the renal parenchyma or the renal pelvis. "Additionally, high expression of HPGD is pointed out as favorable prognostic marker in renal cancer by The Human Protein Atlas." (PMID 29949949, 2018).
renal cell carcinoma (1 paper, 2025). "Molecular docking findings indicate that the environmental endocrine-disrupting chemical BPA specifically interacts with key targets essential for the function of renal cell carcinoma cells, including CHRM3, GABBR1, CCR4, KCNN4, PRKCE, CYP2C9, HPGD, and FASN." (PMID 41301871, 2025).